EGFR (epidermal growth factor receptor)
Diseases named in the same sentence as EGFR in open-access papers (continued):
Sharing a sentence is not in itself a finding about the gene and the disease.
glioma (continued). "Collectively, these findings suggest that H3K23ac/TRIM24/STAT3 signal pathway plays an important role in EGFR/EGFRvIII-driven tumorigenesis in human gliomas." (PMID 29129908, 2017). "Epidermal growth factor receptor (EGFR) has been shown to be overexpressed in a variety of tumors and is one of the significant factors responsible for the development of gliomas." (PMID 28181832, 2017). "EGFR activates the PI3K/Akt pathway in both normal and cancer cells and the EGFR gene amplification in glioma cells induces an constitutive activation of PI3K." (PMID 28629170, 2017). "It was reported that LRIG1 was downregulated in irradiated glioma U251R cells, and its overexpression significantly reduced EGFR signaling and AKT phosphorylation, increasing γH2AX foci formation and the rate of apoptosis." (PMID 29246031, 2017). "Thence, EGFR signaling pathway is certainly the major and probably the unique pathway for the anti-glioma effect of F2." (PMID 29156717, 2017). "We investigated the effects of aquaporin 5 (AQP5) gene silencing on the proliferation, migration and apoptosis of human glioma cells through regulating the EGFR/ERK/p38MAPK signaling pathway." (PMID 28404978, 2017). "Our results indicate an important role of Axl and EGFR signaling in conferring vemurafenib resistance in BRAFV600E glioma." (PMID 27611946, 2017). "This has been mirrored in the treatment of glioma patients with pharmacological inhibitors of EGFR or blocking antibodies that fail to show signs of activity, indicating that inhibition of EGFR alone is insufficient." (PMID 29069805, 2017). "EGFR pathway is upregulated in malignant gliomas, and its downstream signaling is important for self-renewal of glioma cancer stem-like cells (GSC)." (PMID 28410196, 2017). "PAI-1 as well as EGFR are highly expressed in grade IV gliomas, and both are poor prognosis markers for overall survival in glioma patients." (PMID 28629170, 2017). "Although RAS, a downstream effector of EGFR, is one of the most frequently mutated oncogenes in many types of cancer, mutations of RAS in glioma are relatively rare." (PMID 28830458, 2017). "Other research groups reported that knockdown of Notch1 expression by siRNA in U251 glioma cells downregulated the expression of EGFR, indicating the crosstalk and interaction of Notch1 and EGFR signaling pathways." (PMID 28157712, 2017). "The results demonstrated that CNG of EGFR, HER3 and HER4 significantly increased the risk of cancer-related death in glioma patients." (PMID 29190914, 2017). "Similar tagging efficiencies were also observed in the primary mouse foetal FNS2 line and in a glioma-initiating line harbouring Ink4a (Cdkn2a, encoding Ink4a/ARF) and EGFR overexpression." (PMID 28096221, 2017). "In this study, expressions of SSTR2 and EGFR were investigated in both human and rat glial tumor samples (n= 25 each) and all were found immunopositive." (PMID 29029435, 2017). "Additional studies in glioma cell lines and xenograft tumor models revealed that miR-21 knockdown decreased the expression of EGFR, cyclin D, phospho-AKT and Bcl-2, increased autophagy and apoptosis, and induced cell cycle arrest." (PMID 29246031, 2017). "More importantly, EGFR promotes glioma cells survival and chemotherapy resistance through Akt-independent activation of NF-κB pathway." (PMID 28946903, 2017). "In both neural stem cells and glioma CSCs activated EGFR signaling increases proliferation, survival, migration and blocks differentiation." (PMID 29069805, 2017). "Considering that the PI3K/Akt and MEK/ERK1/2 pathways are two major downstream signaling pathways of activated EGFR in glioma, therapeutic approaches for the inhibition of these signaling pathways are being actively studied." (PMID 28830458, 2017). "In contrast, for EGFR, most of the genetic alterations were amplifications, suggesting an over expression during the acceleration of glioma." (PMID 29152101, 2017).
glioma (continued). "Due to this mTORC2 is an essential component for tumor growth in response to enhanced EGFR signal flux through PI3K in glioma, conferring resistance to EGFR inhibitors." (PMID 28491867, 2017). "The hyperactivation of EGFR signaling is a primary contributor to glioma initiation and progression." (PMID 28946903, 2017). "TRIM24 is upregulated by EGFR activation, and is required for EGFR-driven glioma cell proliferation, cell migration, colony formation in soft agar, orthotopic xenograft tumor growth in mouse brain." (PMID 29129908, 2017). "Examination of an array of human glioma cell lines showed substantial EGFR and Axl expression in GBM cells." (PMID 27611946, 2017). "Combined with the previous studies, we only further ascertain the potential role of the EGFR gene to glioma onset." (PMID 28938685, 2017). "Exosomes isolated from the serum of patients with gliomas have been shown to contain EGFR, EGFRvIII, TGF-beta and other proteins and nucleic acid species." (PMID 29383115, 2017). "In this study, we investigated the effects of AQP5 gene silencing on the proliferation, migration and apoptosis of U87-MG and U251 glioma cells through regulating EGFR/ERK/p38 MAPK signaling pathway." (PMID 28404978, 2017). "Intra-tumor injection of EVs carrying miR-146 significantly reduced glioma xenograft growth in a rat model of primary brain tumor by targeting epidermal growth factor receptor (EGFR)." (PMID 29657282, 2017). "Glioma patients exhibited a significantly higher copy number of EGFR (6.53 vs. 1.91; P =0.01), HER2 (3.87 vs. 2.36; P =0.001), HER3 (4.21 vs. 2.09; P =0.01), and HER4 (4.43 vs. 1.98; P =0.01) than control subjects." (PMID 29190914, 2017). "The Epidermal Growth Factor Receptor gene has been reported to be involved in the progression of gliomas which is one of the deadliest primary brain tumors in humans." (PMID 28938685, 2017). "Under reported neurosphere culture conditions, highly invasive glioma cells with amplification of wild-type EGFR have been observed." (PMID 29113349, 2017). "It has been reported that miR-219-5p targets EGFR to inhibit glioma cell proliferation and migration." (PMID 28423675, 2017). "We found that knockdown of BTK significantly suppressed EGFR-induced NF-κB activation in glioma cells." (PMID 28946903, 2017). "Collectively, these findings suggest that TRIM24 plays an important role in EGFR/EGFRvIII-driven tumorigenesis in gliomas." (PMID 29129908, 2017). "Human glioma U87MG or LNZ308 cells overexpressing either wild‐type (wt) EGFR or EGFRvIII were treated with nimotuzumab, temozolomide, or both." (PMID 26778701, 2016). "Nimotuzumab is an EGFR monoclonal antibody that has been approved as an orphan drug for the treatment of glioma and head and neck squamous cell carcinomas and in the process of clinical trials for other solid tumors including NSCLC." (PMID 26988752, 2016). "Different growth factor receptors, such as epidermal growth factor receptor (EGFR), platelet-derived growth factor receptor (PDGFR), C-Kit, vascular endhotelial growth factor receptor (VEGFR), appeared mutated in glioma cells." (PMID 27338365, 2016). "While EGFR amplification and overexpression were previously reported to impact the prognosis of glioma patients, the conclusions of the studies were inconsistent." (PMID 27437777, 2016). "This study found that the expressions of VEGFR-1/2, p-VEGFR-1/2, and EGFR are downregulated after cZNF292 silencing, suggesting that these genes are involved in glioma cZNF292 biology." (PMID 27613831, 2016). "Wnt-independent mechanisms of beta-catenin activation also exist in glioma including the EGF/EGFR pathway." (PMID 27613837, 2016).
glioma (continued). "The Kindlin-2/YB-1/β-catenin complex promotes EGFR transcription and contributes to glioma progression." (PMID 27713156, 2016). "While EGFR is one of the most important oncogenic drivers in glioma, the clinical efficacy of EGFR-targeted therapy has been disappointing." (PMID 26933808, 2016). "Simultaneous up-regulation of Kindlin-2 and silencing of YB-1 or β-catenin in glioma cells resulted in a decrease in EGFR mRNA levels and transcriptional activity, and disruption of the Kindlin-2 binding sites in the EGFR promoter." (PMID 27713156, 2016). "Eighty glioma patients were successfully analyzed for EGFR copy number variation and 1p/19q codeletion, however two samples were excluded since the ratio was below 1 and there were too few patients to make a separate group for these two samples." (PMID 26839018, 2016). "Regions harboring EGFR (7p11.2) or CDKN2A (9p21.3) were the most frequently amplified or deleted region in the RMPAhigh gliomas." (PMID 27385209, 2016). "The Kindlin-2-induced effects were attenuated by EGFR knockdown, suggesting that EGFR transcription is required for Kindlin-2 function in glioma." (PMID 27713156, 2016). "In particular, inherent resistance to these therapies is thought to be secondary to the glioma stem cell compartment’s ability to activate alternative pathways to bypass EGFR upstream signals." (PMID 27043632, 2016). "EGFR, PDGFRA, FGFR1, FGFR2, FGFR4 and MET are frequently amplified, mutated, or fused in high-grade gliomas or in secondary GBMs." (PMID 27385209, 2016). "Nearly half of gliomas overexpress EGFR, which has been functionally related to enhanced tumor cell survival and growth." (PMID 27713911, 2016). "In addition, we evaluated the association between the risk for glioma and pre-diagnostic serum levels of EGFR and ErbB2 using both dichotomized and continuous protein abundance data to understand if chronic activation and high levels of the receptors could be a mechanism in gliomagenesis." (PMID 26906551, 2016). "Collectively, the results indicated that Kindlin-2 formed a complex with YB-1 and β-catenin to regulate EGFR transcription and promote glioma progression." (PMID 27713156, 2016). "Further elucidation of this process will impact not only the understanding of EGFR signaling and functions, but also our view of the use of EGFR-targeting therapies in gliomas." (PMID 27811356, 2016). "For example, a truncated, oncogenic form of EGFR, EGFRvIII, can be transferred between glioma cells via EVs." (PMID 27259278, 2016). "Foxo transcription factors, the critical downstream transcription factors of the EGFR/Akt pathway, are inactivated by cytoplasmic mislocalization in glioma cells." (PMID 27733172, 2016). "We identified significant correlations between five SNPs in EGFR (rs11506105, rs3752651, rs1468727, rs845552 and rs730437) and the prognosis of glioma patients." (PMID 27437777, 2016). "Nano GO carrying epirubicin was conjugated with epidermal growth factor receptor (EGFR) antibody C225 to target against gliomas." (PMID 28540369, 2016). "The over-expression of miR-340 suppressed several oncogenes, including EGFR, and further dramatically inhibited glioma cell proliferation, induced cell-cycle arrest and apoptosis, and promoted autophagy." (PMID 26830677, 2016). "Differentially expressed proteins in this early stage, low-grade gliomas, include important regulatory proteins such as EGFR, HNRNP K and BCAN." (PMID 27246909, 2016). "Investigations on U87 and LN229 glioma cells (with overexpression of EGFR++) showed that the migratory response of cancer cells to radiation is dependent on radiation dose, as well as on cell and radiation type." (PMID 26942125, 2016). "The in vitro studies confirmed that C225 when conjugated with PEG-nano GO does not only target the glioma U87 cells but also inhibits EGFR expression." (PMID 28540369, 2016).
glioma (continued). "It has been demonstrated that Notch-1 promoted proliferation and survival of glioma cells through EGFR/Mcl-1 and mTOR signaling." (PMID 26824182, 2016). "The combined treatment of nimotuzumab (monoclonal antibody against EGFR) and rapamycin effectively enhances glioma cell death in TMZ-resistant glioma cells." (PMID 26830677, 2016). "The high expression of EGFR in brain cancers including glioma has led to its exploitation as a therapeutic target, and we therefore evaluated the potential use of EGFR for targeting Dox-loaded minicells to brain tumor cells." (PMID 27050167, 2016). "In conclusions, the present study has demonstrated that nimotuzumab enhanced the antitumor efficacy of TMZ in human glioma cells overexpressing EGFR, especially the most common mutant EGFRvIII, in vivo." (PMID 26778701, 2016). "The photon-induced increase in cell migration in U87 glioma cells was paralleled by an elevated phosphorylation status of the EGFR and AKT–ERK1/2 pathway." (PMID 26942125, 2016). "Kindlin-2-mediated glioma cell proliferation, migration, and invasion were abolished upon EGFR depletion by siRNA." (PMID 27713156, 2016). "In gliomas, it has been shown that, in response to EGFR inhibitors, upstream and downstream signaling pathways can be linked through the removal (or bypassing) of intermediate modules." (PMID 25885672, 2015). "Collectively, these data support BRAFV600E and EGFR combination therapy as an approach for treating BRAFV600E glioma." (PMID 26023796, 2015). "Several genes including e.g. F5, LAMA1, ERBB2 or STARD3 seems to be in proximity to genes of the EGF/EGFR signaling cascade, which is known to be important in glioma." (PMID 25537509, 2015). "In high-grade gliomas, the frequently occurring oncogenic EGFR mutant EGFRvIII can induce overexpression of both MET and HGF, a process that is balanced by wild-type EGFR activation." (PMID 25862637, 2015). "The present study shows that pUS treatment combined with therapeutic anti-EGFR antibodies enhances the anti-tumor effect in glioma-bearing mice." (PMID 25960704, 2015). "The expression of EGFR is frequently upregulated in human glioma, and its overexpression correlates with poor prognosis." (PMID 25544346, 2015). "This study demonstrated the use of EGFR-targeting MBs combined with pUS exposure to enhance therapeutic EGFR antibody delivery to glioma tumor cells in mice." (PMID 25960704, 2015). "The amplification of EGFR and the expression of EGFRvIII are biomarkers of poor prognosis in glioma patients." (PMID 25644759, 2015). "The high incidence of EGFR overexpression in pediatric high grade gliomas provided the rationale for conducting a pediatric study using EGFR inhibitors." (PMID 26543772, 2015). "The elimination or weakening of the activity of these repressors are observed in tumors, including gliomas, and can shore up resistance against the targeting of the EGFR-driven signaling network." (PMID 25885672, 2015). "In these non-EGFR expressing glioma cells, rapamycin treatment reduces activation of AKT at Serine 473 residue when compared to the untreated or DMSO control group." (PMID 25886314, 2015). "Our results using antibody microarrays suggest that factors released from microglia upregulate PLCγ1 and EGFR protein levels in C6 glioma cells." (PMID 26098895, 2015). "Both total and phosphorylated EGFR were expressed at consistently higher levels in glioma as compared with melanoma cells." (PMID 26023796, 2015). "EGFR gene amplification has been observed in pediatric low-grade gliomas that disseminate possibly through a mechanism of induced FABP7 nuclear translocation." (PMID 26199775, 2015). "On the basis of the implication of EGFR not only in proliferation, but also in migration of glioma cells, we also assayed cell migration and found that it was strongly decreased upon N6L treatment." (PMID 26540346, 2015).
glioma (continued). "Recurrent alterations in EGFR amplified gliomas were both focal, such as CDKN2A homozygous deletions, and large, such as chromosome 10 loss." (PMID 26257825, 2015). "IDHwt lower grade gliomas and grade IV gliomas are closely related and driven by common and well known alterations including EGFR amplification and PTEN deletion, while IDHmut lower grade gliomas remain functionally distinct from grade IV gliomas." (PMID 26091668, 2015). "Recent data of The Cancer Genome Atlas (TCGA) consortium on lower grade (WHO grade II and III) gliomas show that IDH mutations in these gliomas are virtually mutually exclusive with homozygous deletion of CDKN2A and with amplification of EGFR." (PMID 25943885, 2015). "Fixed HNSCC and glioma tissues were analyzed by fluorescence in situ hybridization for EGFR amplification." (PMID 25658924, 2015). "In all lower-grade gliomas examined for EGFR FISH analysis, EGFR amplification was found in 6 of 86 (7%) diffuse astrocytomas and 3 of 63 (4.8%) anaplastic astrocytomas, giving an overall amplification frequency of 4.2% (9/214)." (PMID 26369702, 2015). "TF expression has also been shown to be modulated in other cancers by constitutively active mutant forms of epidermal growth factor receptor (EGFRvIII) in glioma and vulva cells, as well as Src family kinases, TGF-β production, and hypoxia." (PMID 26573921, 2015). "For this, human U87MG glioma cells overexpressing wild-type EGFR (U87MG.wtEGFR; 170 kDa) and mutant EGFRvIII (U87MG.EGFRvIII, 145 kDa), as validated by western blot analysis, were used." (PMID 25886314, 2015). "Our data suggests that BRAFV600E and EGFR combination therapy should be considered for clinical evaluation in BRAFV600E glioma." (PMID 26023796, 2015). "An unfavorable prognostic value of EFEMP1 was also observed in a subtype of gliomas expressing a low level of EGFR." (PMID 26307682, 2015). "It has been previously reported that expression of downstream targets of the PI3K-AKT and EGFR-MAPK pathways increased following serum starvation in gliomas." (PMID 26317790, 2015). "The mechanism by which retinoids inhibit the proliferation of GBM cells is not well understood but it has been shown in different glioma cell lines that the epidermal growth factor receptor (EGFR) can be targeted by all-trans retinoic acid (ATRA)." (PMID 26362268, 2015). "This treatment group showed both inhibition of EGFR-dependent glioma-cell growth and a large number of anti-EGFR monoclonal antibodies." (PMID 25960704, 2015). "This is especially relevant in GBM because it highlights the plausibility of targeting TMZ resistant and EGFR-null glioma cells with alternative combination drugs such as Nimotuzumab and rapamycin." (PMID 25886314, 2015). "Consistently, N6L dramatically decreases both the active form of ErbB1 receptor (EGFR) and ERK1/2, known to be implicated in proliferation, migration and invasion of glioma cells." (PMID 26540346, 2015). "EGFR expression has been observed in a variety of human tumours, such as those in the lung, head and neck, pancreas, ovary, and glioma, and high expression of the receptor has been shown to be associated with poor prognosis in patients with tumours." (PMID 26036864, 2015). "Vice versa, upregulation of EGFR in a telomerase reverse transcriptase- (TERT-) dependent manner allows differentiated glioma cells to acquire stem-like features." (PMID 26136784, 2015). "Our data support clinical evaluation of BRAFV600E and EGFR targeted therapy in treating BRAFV600E glioma." (PMID 26023796, 2015). "EGFR is often overexpressed and amplified in gliomas, and contributes to uncontrolled proliferation and survival of glioma cells." (PMID 25960704, 2015). "We compared EGFR expression and activation in human glioma cell lines, and in relation to several melanoma cell lines representative of a cancer in which RTK signaling is not prominent." (PMID 26023796, 2015).